PCSK9 (proprotein convertase subtilisin/kexin type 9)
Diseases named in the same sentence as PCSK9 in open-access papers (continued):
Sharing a sentence is not in itself a finding about the gene and the disease.
ovarian carcinoma (10 papers, 2021 to 2025). A malignant neoplasm originating from the surface ovarian epithelium. "Notably, PCSK9 expression was significantly associated with five cancer types: brain, colorectal, lung, head and neck, and ovarian cancer." (PMID 37860186, 2023). "Another study on ovarian cancer models, evidenced that PCSK9 is also upregulated in ovarian cancer cells and correlated with tumor invasiveness by direct stimulation of ERK/MEK pathways." (PMID 36900189, 2023). "While a few preclinical studies show the efficacy of PCSK9 inhibition in attenuating cell proliferation and survival of ovarian cancer cells, the clinical impact of anti-PCSK9 agents is yet to be explored in OC." (PMID 37754524, 2023). "The use of PCSK9 blocking monoclonal antibodies or SiRNAs suppresses the growth of ovarian cancer cells by reducing AKT phosphorylation by reducing endogenous lipogenesis in these cells." (PMID 36900189, 2023). "According to the available evidence, lipid-lowering medicines, such as statins, PARP inhibition, fenofibrate, and PCSK9, have been implied to have anti-tumor effects in several human malignancies, including ovarian cancer." (PMID 37781114, 2023). "However, PCSK9 exhibited a protective effect in two other cancer types, brain cancer [OS: total = 67, HR = 0.01, Cox p = 0.030] and ovarian cancer [PFS (progression free survival): total = 110, HR = 0.89, Cox p = 0.044]." (PMID 37860186, 2023). "Importantly, the ectopic overexpression of PCSK9 in JHOS2 ovarian cancer cells significantly induced the expression of AKT/MEK/ERK signaling, which plays an essential role in metastasis in OC." (PMID 37754524, 2023). "It is possible that circulating cholesterol is not the cause of the observed relationship between HMG-CoA reductase inhibition and ovarian cancer due to the lack of genetically close inhibition between NPC1L1 and PCSK9 inhibition and genetically close LDL cholesterol levels." (PMID 36034854, 2022).
venous thromboembolism (10 papers, 2020 to 2025). Occlusion of the lumen of a vein by a thrombus that has migrated from a distal site via the blood stream. "On the other hand, a post hoc analysis of the FOURIER trial treatment with PCSK9 inhibitor evolocumab demonstrated a 46% relative risk reduction in venous thromboembolism (hazard ratio 0.54, 95% CI 0.33–0.88, p = 0.014)." (PMID 35806908, 2022). "PCSK9 variants were associated with central adiposity, venous thrombosis embolism, systolic blood pressure, mood instability, and neuroticism (all p < 1.16 × 10−4)." (PMID 35501368, 2022). "Notably, PCSK9 inhibitors have an effect on the incidence of venous thromboembolism, which is associated with endothelial inflammation and atherogenesis." (PMID 35566668, 2022). "A post hoc analysis of the FOURIER trial (Further Cardiovascular Outcomes Research with PCSK9 Inhibition in Subjects With Elevated Risk) suggested that an increased risk of venous thromboembolism (VTE) was significantly related to the increased Lp (a) but not LDL-C levels." (PMID 33681307, 2021). "An analysis of clinical trials (FOURIER and ODYSSEY OUTCOMES) reported lower rates of venous thromboembolism in patients who were treated with PCSK9 inhibitors compared with placebo." (PMID 35323699, 2022). "Noteworthy is the influence of PCSK9 inhibitors on the incidence of venous thromboembolism, which is related to the inflammatory process in the endothelium and the atherogenesis." (PMID 35323699, 2022).
fibrosis (9 papers, 2021 to 2025). the formation of excess fibrous connective tissue in an organ or tissue in a reparative or reactive process. "In human genetic studies, the PCSK9 rs11591147 loss-of-function (LOF) variant was protective against liver steatosis, nonalcoholic steatohepatitis, and fibrosis." (PMID 33919550, 2021). "PCSK9 expression was also heightened in patients with liver fibrosis and in a fibrosis mouse model (BDL mice) compared to control groups." (PMID 33919550, 2021). "In a mouse model of fibrosis, PCSK9 deletion alleviated hepatic inflammation, accompanied with a reduction in the plasma levels of lipopolysaccharide (LPS), aspartate aminotransferase (AST), and alanine aminotransferase (ALT), which are representative biomarkers of liver injury." (PMID 39963241, 2025). "Another interesting finding of our research was that TGF-β, which is an important regulator of cardiac fibrosis, was upregulated in the PCSK9−/− group compared to the WT group after AMI, which was not completely consistent with the Masson staining results in our study." (PMID 35832650, 2022).
Glucose intolerance (9 papers, 2020 to 2025). Glucose intolerance (GI) can be defined as dysglycemia that comprises both prediabetes and diabetes. "PCSK9 deficiency reduces insulin secretion and promotes glucose intolerance." (PMID 37513689, 2023). "Deficiency of Pcsk9 results in decreased insulin secretion and increased glucose intolerance." (PMID 32527043, 2020). "The anti-PCSK9 vaccine protected VS rats against STZ-induced glucose intolerance and improved glucose sensitivity in the VS group when compared with the DC group." (PMID 34504898, 2021). "An animal study reported that PCSK9-knockout mice exhibited decreased insulin secretion and increased glucose intolerance." (PMID 32708615, 2020).
hypothyroidism (9 papers, 2014 to 2025). Abnormally low levels of thyroid hormone. "Increased total plasma cholesterol in hypothyroidism can also be the result of increased hepatic expression of proprotein convertase subtilisin/kexin type 9 (Pcsk9) stimulated by serum TSH, which was previously shown to be elevated in subclinical hypothyroidism patients." (PMID 37951959, 2023). "There was no such correlation of PCSK9 with FT4, so that effects on PCSK9 were thought to be due to direct effects of TSH on the hepatocyte independent of hypothyroidism." (PMID 24808925, 2014).
Myalgia (9 papers, 2015 to 2025). "Statin intolerance, predominantly caused by myalgia, myositis, and myopathy occurs in 5 % to 20 % of statin-treated patients who will benefit substantially from PCSK9 inhibitor therapy." (PMID 27538393, 2016). "Population exposed to PCSK9 inhibitors would most likely tend to experience myalgia among the five MAE events." (PMID 35140810, 2022). "It was comparable to that of some studies, where myalgia was the most common muscle symptoms attributed to PCSK9 inhibitors." (PMID 35140810, 2022). "The meta-analysis demonstrates that incidence of myalgia is not statistically different between PCSK9 inhibitor-treated groups and control groups and, therefore, it is not likely that PCSK9 inhibitors will induce myalgia any more than conventional treatment." (PMID 36554779, 2022). "PCSK9 inhibitors showed no discernable difference in events of treatment-emergent myalgia when compared to control groups, suggesting that there is no increased incidence of myalgia induced by PCSK9 inhibitors." (PMID 36554779, 2022). "The novel class of PCSK9 inhibitors appears to offer a new option for statin intolerant patients with profound reduction in serum LDL cholesterol without myalgias." (PMID 26703752, 2015).
non-alcoholic fatty liver disease (9 papers, 2020 to 2026). "The link between PCSK9 inhibition and nonalcoholic fatty liver disease (NAFLD) offers intriguing insights into the broader implications of targeting PCSK9 in the context of cardiometabolic aging." (PMID 38105401, 2024). "Age-related fatty degeneration of liver tissue positively correlated with serum PCSK9 levels in the rat model, while development of age-related nonalcoholic fatty liver disease correlated with cardiovascular functional impairment." (PMID 38094682, 2023). "In the same cells, 20 μM resveratrol reduced the expression of PCSK9 and promoted LDL uptake, with important implications for the pathogenesis of non-alcoholic fatty liver disease (NAFLD), the leading cause of liver damage." (PMID 32429343, 2020). "Associations of hepatic PCSK9 protein with lobular inflammation and hepatocyte ballooning were, however, not observed in patients with non-alcoholic fatty liver disease (NAFLD)." (PMID 33920491, 2021). "It was reported that both serum ALT and AST were attenuated by PCSK9 inhibition therapy in alcoholic liver disease and non-alcoholic fatty liver disease (NAFLD), but no previous studies reported the attenuation of aminotransferase by PCSK9 inhibitors in tumor treatment-related hepatotoxicity." (PMID 37025995, 2023).
non-small cell lung carcinoma (9 papers, 2019 to 2024). A group of at least three distinct histological types of lung cancer, including non-small cell squamous cell carcinoma, adenocarcinoma, and large cell carcinoma. "A clinical study of non-small cell lung cancer patients has shown that low systemic levels of PCSK9 (<95 ng/mL) predict better responsiveness to the Programmed Death-1 (PD-1) Inhibitor Nivolumab and have better overall survival than patients with higher blood levels (>120 ng/mL)." (PMID 36900189, 2023). "In addition, several cancer types (e.g., non-small cell lung cancer, cervical squamous cell carcinoma, ESCA, LIHC, SARC, BLCA, and BRCA) had PCSK9 mutations (amplifications or deep deletions)." (PMID 37860186, 2023). "Other studies have advocated that PCSK9 could be a prognostic marker for advanced non-small cell lung cancer and for response to immune checkpoint inhibitors therapy." (PMID 36203122, 2022). "In its recent annual report, the agency published aggregated reports for MPs in some therapeutic areas of interest, such as chronic hepatitis C, age-related macular degeneration, family hypercholesterolemia (PCSK9), and non-small lung cell cancer ALK-inhibitors." (PMID 35782579, 2022). "This study aimed to explore whether PCSK9 expression in tumor tissue could predict the response of advanced non-small cell lung cancer (NSCLC) to anti-PD-1 immunotherapy and the synergistic antitumor effect of the combination of the PCSK9 inhibitor with the anti-CD137 agonist." (PMID 37025995, 2023).
prediabetes (9 papers, 2020 to 2025). "A Chinese study reported on the association between elevated circulating PCSK9 levels and an increased risk for T2D in women with prediabetes." (PMID 33894772, 2021). "The aim of the present study was to determine plasma PCSK9 levels and metabolic profiles of elderly subjects with different glucose tolerance profiles (normal glucose tolerance (NGT), prediabetes (PreDM) and type 2 diabetes (T2D)) under statin therapy." (PMID 33801208, 2021). "We studied the effects of PSCK9 lev-els with different glucose tolerances (normal glucose tolerance (NGT), prediabetes (PreDM) or type 2 diabetes (T2D)) with and without statin medication, and analyzed clinical data, NMR metabolomics and PCSK9 plasma levels." (PMID 33801208, 2021).
type 1 diabetes (9 papers, 2017 to 2025). "PCSK9 is also increased in type 1 diabetes among younger subjects, and plasma PCSK9 levels increased significantly with glycemic control worsening." (PMID 33302966, 2020). "Furthermore, in type-1-diabetes, good glycaemic control abolishes the relationship between PCSK9 and LDL-C indicating a complex and yet not fully interaction between glucose-, LDL-C, and PCSK9 regulation." (PMID 28439730, 2017).
abdominal aortic aneurysm (8 papers, 2018 to 2025). Enlargement and ballooning of the vessel that supplies arterial blood to the abdomen, pelvis and legs. "A causal relationship between PCSK9 and abdominal aortic aneurysms (AAA) has recently been reported." (PMID 41247317, 2025). "PCSK9 directly promotes apoptosis of VSMCs, which is critical for the development of abdominal aortic aneurysms." (PMID 38886277, 2024). "Although there is a lack of clinical trials exploring the effect in aortic aneurysms patients, we believed PCSK9 inhibitor was beneficial to abdominal aortic aneurysm patients." (PMID 34834523, 2021). "Myocardin may be involved in the PCSK9-induced dedifferentiation of VSMCs and thus contributes to the formation of abdominal aortic aneurysms." (PMID 38886277, 2024).
alcohol use disorder (8 papers, 2019 to 2021). "Recent studies have associated elevated PCSK9 with alcohol use disorder, including the interesting possibility of using anti-PSCK9 monoclonal antibodies for the treatment of alcoholic liver disease." (PMID 33886544, 2021). "It has been reported that only SLC1A6 and PCSK9 were associated with MA and/or ethanol abuse." (PMID 33192735, 2020). "The association between mood disorders and PCSK9 levels have received a significant contribution from a recent study on subjects affected by alcohol use disorder showing that PCSK9 cerebrospinal fluid levels are associated with the severity of behavioral disturbances." (PMID 33143700, 2020). "Alcohol use disorder (AUD) causes hypomethylation in PCSK9 promoter and consequently reduces PCSK9 expression and plasma cholesterol levels in a mouse model of AUD, which may partially contribute to the protective effect on CVD risk observed in light alcohol users." (PMID 34782856, 2021). "Alcohol upregulates PCSK9 expression in the brain, as PCSK9 levels in the CSF of patients with alcohol use disorder (AUD) were significantly higher compared to controls." (PMID 32595449, 2020). "In addition, plasma PCSK9 levels were found to correlate positively with PCSK9 levels in the CSF of patients with alcohol use disorder." (PMID 33947873, 2021). "Future studies are needed to elucidate the exact role of PCSK9 in ALD and alcohol use disorder (AUD) and to evaluate efficacy and safety of anti-PCSK9 treatment in clinical populations with ALD/AUD." (PMID 31748600, 2019). "A cross-tissue and cross-phenotypic analysis of genome-wide methylomic variation performed in alcohol use disorder (AUD) using samples from three discovery, four replication, and two translational cohorts indicated that replication in the AUD datasets confirmed PCSK9 hypomethylation." (PMID 33192735, 2020).
asthma (8 papers, 2021 to 2025). "Their Mendelian randomization study indicates a causal relationship between PCSK9 inhibitors and an increased risk of asthma." (PMID 38623319, 2024). "We revealed significant heterogeneity (p = 4.53x10-3) and horizontal pleiotropy (p = 1.49x10-2) when we investigated the causality between the inhibition of PCSK9 and asthma." (PMID 37580807, 2023). "After performing a drug target MR analysis, we found genetically predicted inhibition of PCSK9 significantly reduced the risk of SLE but increased the risk of asthma and CD." (PMID 37580807, 2023). "Further research exploring these potential mechanisms and conducting meta-analyses to synthesize evidence from multiple studies could provide a more comprehensive understanding of the complex relationship between PCSK9 inhibitors and asthma risk." (PMID 38623319, 2024). "PCSK9 inhibitor significantly reduced the risk of SLE but increased the risk of asthma and CD." (PMID 37580807, 2023). "Encouragingly, our updated analysis still demonstrated that the inhibition of PCSK9 was associated with a significantly increased risk of asthma (IVW: OR [95%] = 1.15 [1.03 to 1.29], p = 1.68 × 10−2), and this result exhibited no significant heterogeneity or horizontal pleiotropy." (PMID 37580807, 2023). "Conversely, the present study also indicated that PCSK9 inhibition is potentially associated with higher risks of URTI, acute exacerbation of COPD, and asthma." (PMID 38198221, 2024). "PCSK9 inhibitor significantly reduced the risk of SLE (OR [95%CI] = 0.47 [0.30 to 0.76], p = 1.74 × 10−3) but increased the risk of asthma (OR [95%CI] = 1.15 [1.03 to 1.29], p = 1.68 × 10−2) and CD (OR [95%CI] = 1.38 [1.05 to 1.83], p = 2.28 × 10−2)." (PMID 37580807, 2023). "In addition to confirming the expected associations with various forms of occlusive CVD, we further identified that PCSK9-GS, orientated to a lowering of LDL-C, was associated with a higher risk of URTI, acute exacerbations of COPD, and self-reported asthma." (PMID 38198221, 2024). "We also replicated associations for a PCSK9 variant, reported in UK Biobank, with increased risks of acute upper respiratory tract infection (URTI) [pooled OR after meta-analysis of 1.87 (1.38–2.54); P = 5.4 × 10−5] and self-reported asthma [pooled OR of 1.17 (1.04–1.30); P = 0.0071]." (PMID 38198221, 2024).
carotid atherosclerosis (8 papers, 2020 to 2025). A thickening and loss of elasticity of the walls of carotid arteries that occur with formation of atherosclerotic plaques. "The development of carotid atherosclerosis may not only be dependent on the concentration of PCSK9 but also on the single nucleotide polymorphisms (SNPs) that affect PCSK9." (PMID 36768292, 2023). "Moreover, several longitudinal studies suggested that higher PCSK9 concentration was associated with the development of carotid atherosclerosis in populations free of cardiovascular disease (CVD) at baseline." (PMID 33738300, 2021). "In fact, the clinical value of PCSK9 as a potential marker for subclinical carotid atherosclerosis has been investigated in a large cohort." (PMID 38402551, 2024). "Additionally, a cohort study indicated that plasma proprotein convertase subtilisin/kexin type 9 (PCSK9) levels were positively correlated with 10-year progression of carotid atherosclerosis beyond LDLc." (PMID 32660519, 2020).
cerebrovascular disease (8 papers, 2017 to 2026). "In recent years, numerous clinical studies have demonstrated the effectiveness of PCSK9 inhibitors in significantly reducing cardiovascular and cerebrovascular disease by markedly lowering LDL-C levels." (PMID 39767636, 2024).
dementia (8 papers, 2020 to 2026). Loss of intellectual abilities interfering with an individual's social and occupational functions. "Using another FHS dataset with 3,048 individuals with genetic data, we examined the association between PCSK9 genotypes and the incidence of AD/dementia, stratifying the analysis based on APOE ε4 status." (PMID 41737429, 2026). "Long-term safety data and follow-up analyses from these studies have offered early hints of a possible connection between PCSK9 and dementia risk." (PMID 41465790, 2025). "Lastly, we demonstrate a novel association between genetically determined reduction in PCSK9 function and protection against dementia." (PMID 33166319, 2020). "Of our non-atherosclerotic endpoints, genetically determined reduced PCSK9 function was associated with a reduced risk of dementia in trans-ethnic meta-analysis." (PMID 33166319, 2020). "We found a significant reduction in the risk of all-cause dementia amongst individuals with genetically reduced PCSK9 expression." (PMID 33166319, 2020). "Genetically reduced PCSK9 function associated with a reduced risk of dementia in trans-ethnic meta-analysis (OR 0.86 [95% CI 0.78–0.93], p = 5.0 x 10−04)." (PMID 33166319, 2020). "Mendelian randomization studies of individuals with lifelong low LDL-C due to PCSK9 and hydroxy-3-methylglutaryl-CoA reductase variants show no increased dementia risk." (PMID 40648946, 2025). "An effect of PCSK9, ANGPTL4, and LPL variants on dementia risk cannot be excluded." (PMID 41059729, 2025).